RB1 (RB transcriptional corepressor 1)
Diseases named in the same sentence as RB1 in open-access papers (continued):
Sharing a sentence is not in itself a finding about the gene and the disease.
tumor (continued). "Subsequently, IHC staining for RB1 protein was performed, and showed complete loss of normal constitutive nuclear expression in tumor cells, with retained expression in tumor vascular endothelial nuclei." (PMID 33827698, 2021). "For instance, in a whole-exome sequencing analysis of one or more tumor foci from 18 patients following 24 weeks of neoadjuvant leuprolide and abiraterone, Sowalsky et al31 identified enrichment of RB1 loss in residual disease." (PMID 34322653, 2021). "Homozygous RB1 loss has been observed more frequently in metastatic BC, especially BCBrM, as compared to primary tumor sites." (PMID 35145903, 2021). "To determine if Rb1 loss promotes castration resistance in the context of PN mice, we performed longitudinal magnetic resonance imaging (MRI) analyses to track tumor growth before and after castration at 12 weeks of age." (PMID 34099734, 2021). "We have demonstrated that the AH is a rich source of cell-free tumor-derived DNA (ctDNA) that captures the genomic landscape of RB tumors, including RB1 mutations and RB SCNAs10,11." (PMID 34316014, 2021). "Secondly, tumour molecular characteristics (e.g., the presence of RB1 mutations) and the high metabolic and replicative activities exhibited by tumour cells support the preferential replication of OVs within tumour cells." (PMID 34452316, 2021). "Only biallelic RB1-mutated or knockout hESCs with the loss of RB protein function can be used effectively to generate Rb tumor." (PMID 33899024, 2021). "Tumours with simple point mutations and deletions of RB1 harboured a lower incidence of structural rearrangements (average 6, range 1–15)." (PMID 33670346, 2021). "Upon mutation of both alleles of the tumor suppressor RB1 gene, cells from the retina abnormally proliferate to create a tumor mass that disrupts intraocular structures." (PMID 33430814, 2021). "In RB1 deficient tumor cells, apoptosis evasion mechanisms also add to the complexity of the SCLC genome." (PMID 34531756, 2021). "First, it facilitates tumor-directed mutational analyses to improve sensitivity of peripheral blood testing for germline RB1 mutations." (PMID 33805776, 2021). "In this RB1 wild-type tumor, the biallelic loss of CDKN2A was potentially targetable with CDK4/6 inhibitors." (PMID 33580196, 2021). "RB1 pathogenic variants were identified in tumour and genomic DNA using MSK-IMPACT, a NGS panel that targets over 400 genes associated with cancer, including all coding exons of RB1." (PMID 33805427, 2021). "Bilateral tumours obtained from one patient harboured conserved germline but divergent somatic RB1 mutations, indicating independent evolution." (PMID 33670346, 2021). "A small amount of aqueous humor aspirate, as little as 0.1 ng/μl, can help detect RB1 mutations and determine tumor zygosity based on mutated RB1 allele frequency." (PMID 34195690, 2021). "We reported a 95% efficacy of RB1 mutation screening in our early studies, when enucleation was an inevitable treatment option and tumor samples were available for each proband under study." (PMID 34680218, 2021). "Subsequently, Rb tumours with mutation of both RB1 alleles and also amplification of MYCN were discovered." (PMID 33670346, 2021). "Instead, epigenetic deregulation of tumor-promoting pathways cooperating with the loss of RB1 has been shown to be required for tumorigenesis." (PMID 34003213, 2021). "Consistent with previously published work, this suggests that the number of SCNAs a tumor develops is dependent on the length of time from initial tumorigenesis (biallelic RB1 loss or RB1-null cone precursor proliferation) to diagnosis." (PMID 34283049, 2021).
tumor (continued). "In the remaining non-hereditary cases, RB is caused by a somatic mutation, leading to biallelic RB1 loss in the tumor only." (PMID 34316014, 2021). "RB1 mutations are linked to chromosomal rearrangements that subsequently disrupt genes that inhibit tumor growth and progression." (PMID 35145903, 2021). "We propose that genes that scored at all steps of our pipeline (Subset 3 at S3 Table) are the most attractive targets for treatment of human cancers with RB1-deficiency and more likely to kill RB1-deficient cells in highly heterogeneous tumor cells." (PMID 33591981, 2021). "A meta-analysis of four studies reporting high-throughput sequencing data for SCLC revealed that RB1 plays a pivotal role in tumor progression and the subsequent mutation burden of SCLC." (PMID 33801812, 2021). "RB1 is the first tumor suppressor gene identified whose mutational inactivation would lead to the formation of a tumor." (PMID 34639028, 2021). "Complete loss of chromosome 13 is associated with more aggressive malignancy than partial loss, in part because tumor suppressors such as RB1 reside there." (PMID 33963182, 2021). "As this gene set represents genes typically downregulated by Rb1, these data suggest that the chr14 deletion contributes to the loss of the tumor-suppressive function of Rb1." (PMID 33435218, 2021). "As a highly malignant tumor, RB usually manifests in the first three years of life and represents the prototypic pattern for inherited tumors, with the tumor initiated by the somatic inactivation of both alleles of the RB gene (RB1)." (PMID 33810621, 2021). "This somatic RB1 mutation was similarly identified in the matched tumor sample obtained after enucleation of the left eye (tumor VAF 92%)." (PMID 34316014, 2021). "Since the 1980s, the RB1 gene on the long arm of chromosome 13 (13q14) has been recognized as the RB tumor suppressor gene for the first time, and its pathogenic variant is involved in the occurrence of RB." (PMID 34336010, 2021). "Fourteen (47%) NEC tumours showed distinct alterations in RB1, accompanied by loss of Rb1 and overexpression of p16 by immunohistochemistry." (PMID 33737597, 2021). "Patients with germline RB1 mutations have an earlier age of onset because they only require inactivation of the remaining RB1 allele for tumor initiation." (PMID 34315877, 2021). "RB1 alterations in 8/30 (27%) tumours presented predominantly as homozygous biallelic deletions, and activating RB1 mutations were observed in 6 (20%) tumours." (PMID 33737597, 2021). "It should also be noted that it is unlikely that the same hits would produce SL interactions across all RB1-deficient tumor types." (PMID 33591981, 2021). "Beyond substantiating the presence of tumor-derived cfDNA, identification of somatic RB1 mutations in such a liquid biopsy has clear clinical utility." (PMID 33805776, 2021). "Since disruption of the oncosuppressive RB1 pathway is an almost universal hallmark of human cancers, including MM, dl922-947 can kill tumor cells, while sparing normal cells in which the RB1 pathway is functional." (PMID 33020398, 2020). "Tumor‐guided genotyping detected 10 of the 13 expected somatic RB1 mutations in plasma cfDNA in 8 of 10 patients (average variant allele frequency 3.78%)." (PMID 32633890, 2020). "We further tested the efficacy of GLUT1 inhibition and its association with RB1 protein expression in PDX-derived tumor ex vivo explant models (PDXDEs)." (PMID 32826891, 2020).
tumor (continued). "Based on the RB1 mutations reported in tumor sequencing, we first attempted to genotype those mutations in the corresponding cfDNA using the criteria outlined in the Methods." (PMID 32633890, 2020). "Patients with germline RB1 mutations are predisposed to Rb, and account for 75–80% of bilateral cases and 15–25% of unilateral cases of this tumor." (PMID 32218800, 2020). "The functional analysis of single copy loss of RB1 is very limited, although studies do suggest the loss of a single copy of RB1 is sufficient to contribute to disease relevant phenotypes in mouse and human tumor models." (PMID 32242058, 2020). "RB1, encoding for the retinoblastoma protein, is an intensively studied tumor suppressor that controls cell cycle progression by repressing the family of E2F transcription factors." (PMID 33266490, 2020). "To determine the significance of single copy loss of RB1 we evaluated the relationship with the expression of RB1, and found that in the majority of tumor types single copy loss reduces RB1 expression levels." (PMID 32242058, 2020). "These tumor types also show high frequency of RB1 gene mutations/deletions (instead of cyclin/CDK/CDKI mutations), such as small-cell lung cancer, bladder cancer, breast cancer and hepatocellular carcinoma." (PMID 32509443, 2020). "In both cases, the loss of RB1 protein function, which is a tumor suppressor located on chromosome 13q14, promotes uncontrolled cell division in retinal cells determining tumor formation." (PMID 32545553, 2020). "The absence of cumulative effects from Men1 and Rb1 mutations leads to the suggestion that Menin and pRB are in the same molecular pathway of tumor suppression." (PMID 32733644, 2020). "Sanger sequencing was performed to detect RB1 genetic variants in the patient, his daughter and tumor tissue from his daughter." (PMID 31997559, 2020). "The tumor of case #2 was found to harbor a stop mutation in exon 17 of the RB1 gene (NM_000321.2): c.1654C>T/p.(Arg552Ter)." (PMID 33294214, 2020). "The VAF of RB1 variant (p.E672Q) was 47.3% in HGSC-1 tumour and 92.2% in HGSC-1 organoid, which indicates that the RB1 wild type allele was lost during organoid development." (PMID 32724113, 2020). "We uncovered that miR-181a mediated repression of RB1 initiated tumor formation, caused profound DNA damage, and increased nuclear defects as well as GI." (PMID 32591511, 2020). "The level of tumor‐derived cfDNA in plasma likely drops after systemic chemotherapy, thus hindering the ability to detect the RB1 mutations in cfDNA." (PMID 32633890, 2020). "If tumor tissue is not obtained; a molecular diagnosis cannot be made to determine if the evolution of the patient's tumor derived from somatic mutations only and this hinders definitive clinical RB1 genetic testing and counseling." (PMID 32633890, 2020).
tumor (continued). "Familial RB is distinctly associated with the RB1 tumor-suppressor gene, which encodes pRB, a crucial regulator of the cell cycle." (PMID 33194750, 2020). "Tumor formation is because of the loss of function mutation in both the alleles of the RB1 gene present in chromosome 13q." (PMID 32992741, 2020). "The tumor is initiated through biallelic loss of tumor suppressor gene RB1 in more than 95% of cases, and develops after additional genetic/epigenetic changes." (PMID 32824373, 2020). "The loss of single copy of RB1 is associated with prognosis in specific tumor types, including those that rarely delete RB1 (e.g., KIRC-clear cell kidney cancer)." (PMID 32242058, 2020). "It has been reported that loss of RB1 can enhance the sensitivity of tumor cells to genotoxic agents such as radiations and hormonal therapies." (PMID 35047986, 2020). "These analyses encompass cell cycle genes (e.g., AURKA and CHEK1) that have been shown to be preferentially actionable against RB1 deficient tumor models." (PMID 32242058, 2020). "Results showed that rs137853294 polymorphism (OR, 2.272; 95% CI, 0.088–0.084; P=0.024) and rs121913300 polymorphism of RB1 (OR, 0.264; 95% CI, 0.082–0.0851; P=0.026) showed positive association with tumor grades." (PMID 32373934, 2020). "RB1 mutations with tumor size ≤ 5 cm or tumor size > 5 cm were associated with poor DFS of HBV‐related HCC patients." (PMID 32017470, 2020). "Tumor‐specific somatic RB1 mutations were identified by MSK‐IMPACT from enucleation samples of all 10 patients." (PMID 32633890, 2020). "The 2 RB1 mutated tumors had best overall response of PD, while the 1 tumor with CCNE1 amplification had SD." (PMID 33194700, 2020). "Molecular testing confirmed that RB170 tumor tissue had a wild-type copy of RB1, even though there was evidence of loss of heterozygosity spanning RB1 detected only in the tumor (47 Mb)." (PMID 33270844, 2020). "Genes of cell cycle progression such as CDKN2A and RB1 were more frequently mutated in LUSC tumours." (PMID 31461552, 2019). "Despite the change in tumor size, the MAFs from plasma samples increased minimally except for the newly acquired RB1 mutation, suggesting plasma was relatively insensitive to local disease progression." (PMID 31534501, 2019). "On the other hand, the RB1 loss-of-function signature (designed to predict the absence of benefit to CDK4/6 inhibitors) was also a key characteristic of AFP-high tumours." (PMID 31285588, 2019). "It presents during childhood and infancy and is caused by a mutation in RB1—the first identified tumor suppressor gene." (PMID 31835688, 2019). "The more common presentation is with unilateral, unifocal disease; the vast majority of these children have a sporadic, somatic pathogenic RB1 mutation which is present in the tumor only." (PMID 31835688, 2019). "Although the majority of unilateral RB cases are caused by isolated, somatic genetic defects (in the tumor only), up to 15% of children with unilateral RB have an underlying germline mutation in the RB1 gene (similar to patients with bilateral disease)." (PMID 31835688, 2019).
tumor (continued). "This critical advance allows for the identification of both somatic RB1 mutations, which can aid in tumor-directed mutational analysis of the peripheral blood." (PMID 31835688, 2019). "Loss of the RB1 protein, pRB, results in de-regulated activity of the E2F transcription factors, chromatin changes and developmental defects leading to tumor development." (PMID 29868118, 2018). "The first tumor suppressor gene to be molecularly defined was the retinoblastoma susceptibility gene (RB1)." (PMID 29443735, 2018). "When examined in tumor-bearing animals in vivo, RB1 loss translated into decreased immune infiltration into the tumor microenvironment." (PMID 30400835, 2018). "The tumor occurs due to the loss of the tumor suppression functions of the RB1 gene which is the result of a biallelic mutation." (PMID 29533992, 2018). "To confirm that the effect was due to introduced rb1 mutations, we dissected the dorsal fin (tumor) and tail fin (control normal tissue) from the same adult zebrafish for sequence analysis." (PMID 30061297, 2018). "While the initiation of RB occurs as a result of RB1 biallelic loss, recurrent genomic gains and losses drive tumor progression." (PMID 30353124, 2018). "We have previously shown tumors lacking a T cell-inflamed gene signature (a predictor of immunotherapeutic efficacy) are enriched for loss of the tumor suppressor RB1." (PMID 30400835, 2018). "Whilst in papillary tumours, genetic alterations are mainly restricted to these genes, high risk NMIBC and MIBC often show alterations of major tumour suppressor genes as RB1 or TP538,9." (PMID 30258198, 2018). "We show that loss of RB1 results in an immunosuppressive tumor microenvironment, and that Rb-deficient tumor cells have increased susceptibility to BET inhibition in terms of tumor cell-intrinsic and extrinsic efficacy." (PMID 30400835, 2018). "Our staining for phospho-Rb1 is suggestive that the majority of the tumor cells are deficient for this tumor suppressor." (PMID 30061297, 2018). "The role of ATM or RB1 mutations as potential predictive or prognostic biomarkers has been reported in different tumor studies." (PMID 29682192, 2018). "The role of p16 in suppressing spontaneous tumor formation in RB1-deficient lungs was investigated in vivo by generating double transgenic Scgb1a1-rtTA/tetCre mice wherein RB1 ablation was targeted to the lung epithelium in a p16+/− and p16−/− background." (PMID 28414317, 2017). "Provocatively, there are also low penetrance mutations in human RB1 that target this region of pRB; further suggesting the N-terminus contributes to pRB’s proliferative control and tumor suppressor functions." (PMID 28293272, 2017). "RB1 mutations are very rare in cervical cancers because HPV E7 activity inactivates Rb tumor suppression activity by disrupting its interaction with the transcription factor E2F, making mutations in this gene unnecessary in HPV-positive cancers." (PMID 28771191, 2017). "The top five genes were protein-coding genes with copy number loss in more than 23 cancer types, including canonical tumor suppressor genes RB1 and PTEN." (PMID 29657279, 2017). "Mutation frequency in tumor tissues from rb1 TALEN-injected F0 tp53e7/e7 zebrafish varied from 66.6% (32/48) to 83.3% (40/48), while the frequency in cdkn2a/b TALEN-injected F0 tp53e7/e7 zebrafish varied from 81.3% (39/48) to 91.6% (44/48)." (PMID 28903419, 2017).